CTHRC1 (collagen triple helix repeat containing 1)
Diseases named in the same sentence as CTHRC1 in open-access papers (continued):
Sharing a sentence is not in itself a finding about the gene and the disease.
colon carcinoma (16 papers, 2012 to 2026). "The ROC curves indicated that CTHRC1 is an important risk factor for adjuvant diagnosis of these three tumors, with the highest diagnostic value in colon cancer." (PMID 39052013, 2024). "CTHRC1 upregulation was significantly associated with demethylation of the CTHRC1 promoter in colon cancer cell lines and tumor tissues." (PMID 24504172, 2014). "Here, we provide the first evidence that host-derived CTHRC1 drives colon cancer progression, with this effect consistently observed across three independent cohorts." (PMID 42191349, 2026). "In colon cancer, CTHRC1 was shown to promote proliferation, migration, and invasion via activation of the Wnt/PCP pathway." (PMID 39052013, 2024). "Clinicopathological features, including tumor infiltration depth/clinical stage, and tumor size/lymph node metastasis/clinical stage, were positively correlated with CTHRC1 expression levels in colon cancer and thyroid cancer, respectively." (PMID 39052013, 2024). "In clinical tissue studies, colon cancer and thyroid cancer patients with the BRAF(V600E) mutation showed elevated CTHRC1 expression and immune cell infiltration." (PMID 39052013, 2024). "The OS rates of colon cancer patients with high CTHRC1 expression were significantly lower than those of colon cancer patients with low CTHRC1 expression (P ═ 0.035); similarly, a consistent trend was observed in thyroid cancer patients (P ═ 0.020)." (PMID 39052013, 2024). "In colon cancer and thyroid cancer patients, CTHRC1 expression levels were negatively associated with OS, and univariate COX regression analysis showed that CTHRC1 was an important risk factor correlated with patient OS rates." (PMID 39052013, 2024). "Expression levels of CTHRC1 were significantly correlated with tumor infiltration depth and clinical stage in colon cancer patients and with tumor size, lymph node metastasis, and clinical stage in thyroid cancer patients." (PMID 39052013, 2024). "This indicated that the expression levels of CTHRC1, FBN2, NTM, PDGFC, and PDLIM3 genes are associated with the modulation of immune and stromal activity in the colon cancer tumor microenvironment." (PMID 35991839, 2022). "In summary, these results indicated that the expression of CTHRC1, FBN2, NTM, PDGFC, and PDLIM3 is associated with tumor progression and metastasis of colon cancer cells." (PMID 35991839, 2022). "Altogether, these results indicate the expression of CAFs-derived key transcriptomes (CTHRC1, NTM, and PDGFC) is associated with poor survival prognosis, immunosuppression, tumor progression, and metastasis in human colon cancer." (PMID 35991839, 2022). "Consistent with this, siRNA-mediated CTHRC1 knockdown significantly reduced the invasivity of colon cancer cells." (PMID 24504172, 2014). "Collectively, these results suggest that CTHRC1 acts through ERK-mediated upregulation of MMP9 to promote increased invasiveness of colon cancer cells." (PMID 24504172, 2014). "CTHRC1 gain-of-function and the resulting increased invasion of colon cancer cell lines, demonstrated here, suggest that CTHRC1 has a crucial role in tumor invasion and metastasis." (PMID 24504172, 2014). "A comparison of CTHRC1 transcript levels in colon cancer tissues and normal tissue confirmed these results." (PMID 24504172, 2014). "Therefore, the BRAF(V600E) mutation was associated with CTHRC1 expression, and both were correlated with immune cell infiltration including CD4+ T cells, CD8+ T cells, and neutrophils, in colon cancer and thyroid cancer patients." (PMID 39052013, 2024). "MAFB and CTHRC1 showed significant gene amplification in colon cancer tissues." (PMID 38577604, 2024). "Since the expression levels of CTHRC1, FBN2, NTM, PDGFC, PDLIM3, and SLC16A3 are significantly differentiated among the normal samples, primary tumor, and metastatic tumor, we anticipated that these genes are associated with metastasis in colon cancer." (PMID 35991839, 2022).
colon carcinoma (continued). "Finally, we validated the expression levels of these key genes in the colon tumor stroma dataset, and we revealed that the CTHRC1, NTM, PDGFC, and FBN2 genes are consistently altered in colon tumor stroma." (PMID 35991839, 2022). "Moreover, the overexpression of CTHRC1 correlated with poor prognosis in patients with CRC (especially colon cancer)." (PMID 30302922, 2018). "In this study, we first described the aberrant elevated expression of CTHRC1 in colon cancer, which suggests that CTHRC1, which is slightly expressed in normal mucosal epithelial tissues, may be a novel oncogene." (PMID 24504172, 2014). "In addition, up-regulation of CTHRC1 resulted in an elevated invasion of colon cancer cells, but this process is significantly reduced by siRNA-mediated CTHRC1 knockdown." (PMID 25238260, 2014). "CTHRC1 might play an important role in immunotherapy for colon cancer and thyroid cancer." (PMID 39052013, 2024). "Since the upregulated group of CTHRC1, NTM, PDGFC, PDLIM3, and SLC16A3 and the downregulated group of FBN2 genes are consistently correlated with the shorter survival time in TCGA and GEO datasets, we investigated the association of these genes with immune score and stromal scores in colon cancer." (PMID 35991839, 2022). "Interestingly, CTHRC1 upregulation has better prognostic value for colon cancer than for rectal cancer, which may shade new light on precise postoperative management of CRC patients." (PMID 30302922, 2018). "The upregulation of CTHRC1, PDGFC, PDLIM3, NTM, and SLC16A3 and downregulation of FBN2 are correlated with a shorter survival time in colon cancer." (PMID 35991839, 2022). "We found that upregulated group of CTHRC1, NTM, PDGFC, PDLIM3, and SLC16A3 genes are consistently correlated with the shorter survival of colon cancer patients in GSE17536." (PMID 35991839, 2022). "Multivariate Cox analyses showed that CTHRC1 expression was an independent prognostic factor for OS in all CRC patients (P = 0.010), especially in colon cancer patients (P = 0.001)." (PMID 30302922, 2018). "To determine the function of CTHRC1 as a putative oncogene in colon cancer cells, we examined cell proliferation, β-catenin activity, and invasiveness in a CTHRCl-overexpressing SW480 cell line (SW480-CTHRC1)." (PMID 24504172, 2014). "In an initial attempt to evaluate CTHRC1 and NFE2L3 as biomarkers for cancer and the obtained antibodies for their identification, the DAS- ELISA was used to measure CTHRC1 and NFE2L3 in colon cancer cells using known colon cancer cell lines as a model." (PMID 22321245, 2012). "Interestingly, we found that the expression levels of CTHRC1, FBN2, NTM, PDGFC, and PDLIM3 are positively correlated with the ssGSEA scores of metastatic-promoting genes in colon cancer (Spearman’s correlation test, p < 0.001)." (PMID 35991839, 2022). "Furthermore, the CTHRC1, FBN2, PDGFC, PDLIM3, and NTM genes are positively correlated with the metastatic scores in colon cancer." (PMID 35991839, 2022). "Finally, the expression level of CTHRC1, PDGFC, and NTM genes are consistently altered in colon tumor stroma as well as in the higher CAFs-group of TCGA COAD patients." (PMID 35991839, 2022). "Finally, we investigated the correlation of CTHRC1, FBN2, NTM, PDGFC, PDLIM3, and SLC16A3 with the metastatic scores in colon cancer data." (PMID 35991839, 2022). "Among the upregulated stromal cell-enriched proteins, some proteins have been reported to be potential markers in colon cancer prognosis or tumorigenicity, such as collagen XII (COL12A1), thrombospondin 2 (THBS2), collagen triple helix repeat-containing protein 1 (CTHRC1) and COL5A2." (PMID 26338966, 2015). "Although MMP9 was detected in some CTHRC1-negative patients, CTHRC1 was expressed in most colon cancer patients, and CTHRC1-positive tissues expressed MMP9." (PMID 24504172, 2014).
colon carcinoma (continued). "Univariate analyses indicated that CTHRC1 protein expression correlated with DFS only in patients with colon cancer (P = 0.003), whereas CTHRC1 expression was correlated with OS in patients with colorectal (P = 0.002) or colon cancer (P = 0.000) but not rectal cancer." (PMID 30302922, 2018).
non-small cell lung carcinoma (14 papers, 2014 to 2024). A group of at least three distinct histological types of lung cancer, including non-small cell squamous cell carcinoma, adenocarcinoma, and large cell carcinoma. "Similarly, other cancers, including non-small cell lung cancer, colon adenocarcinoma, and oral cancer, have also demonstrated a close association with CTHRC1." (PMID 38937712, 2024). "In a recent study, CTHRC1 serves as a prometastatic gene of non-small cell lung cancer, and the invasion and metastasis ability mediated by it were MMP7- and MMP9-dependent." (PMID 33564303, 2021). "According to our previous studies, CTHRC1 overexpression was significantly correlated with metastasis in patients with non-small cell lung cancer (NSCLC)." (PMID 31798347, 2019). "Previous studies revealed that the forced expression of CTHRC1 facilitated cancer cell proliferation, invasion and metastasis in epithelial ovarian cancer and non-small cell lung cancer in vitro through the Wnt/β-catenin signaling pathway." (PMID 29234238, 2017). "In addition, CTHRC1 induces non-small cell lung cancer invasion by upregulating MMP-7/MMP-9." (PMID 34968391, 2021). "However, the expression profile of CTHRC1 and its clinical significance in non-small cell lung cancer (NSCLC) remain unknown." (PMID 25238260, 2014).
cervical carcinoma (13 papers, 2014 to 2023). A carcinoma arising from either the exocervical squamous epithelium or the endocervical glandular epithelium. "As a secreted protein, we determined the diagnostic value of CTHRC1 for cervical cancer patients." (PMID 28303973, 2017). "CTHRC1 is also increased in cervical cancer and promotes cell migration and invasion in vitro and metastasis in vivo." (PMID 36982551, 2023). "In cervical cancer, CTHRC1 cooperates with E6/E7 human papillomavirus (HPV) to activate the noncanonical Wnt/PCP pathway, which aggravates tumor malignancy." (PMID 32848510, 2020). "We also demonstrated the molecular mechanism of how E6/E7 regulates the expression of CTHRC1, which provides a new evidence for E6/E7 promoting cervical cancer metastasis by modulating microenvironmental factors." (PMID 28303973, 2017). "Our results showed that CTHRC1 promotes cervical cancer cell migration and invasion in vitro and metastasis in vivo." (PMID 28303973, 2017). "As serum squamous carcinoma antigen (SCC-Ag) value is a clinical-used diagnostic marker for cervical cancer, we drew ROC curve of CTHRC1, SCC-Ag and combined CTHRC1 and SCC-Ag to assess the value of CTHRC1 as a serum marker for cervical cancer." (PMID 28303973, 2017). "CTHRC1 is highly expressed in cervical cancer tissue and serum and closely correlated with clinicopathological parameters." (PMID 28303973, 2017). "For diagnosing cervical cancer, the overall classification accuracy of CTHRC1 was 69.4%, with 48.7% sensitivity and 86% specificity." (PMID 28303973, 2017). "CTHRC1 overexpression in these two cervical cancer cells was confirmed by qPCR and western blotting." (PMID 28303973, 2017). "In this study, by silencing E6/E7 in HPV16 and HPV18 infected cervical cancer cells, we found that E6/E7 can regulate many microenvironment factors, like CTHRC1." (PMID 28303973, 2017). "A multivariate function combining measurement of serum concentrations of SCC-Ag and CTHRC1 improved overall sensitivity for detection of cervical cancer to 88.2%." (PMID 28303973, 2017). "The results showed the serum CTHRC1 levels of cervical cancer patients, CIN patients and healthy people are 12.1 ± 0.89 ng/ml, 8.157 ± 0.5100 ng/ml and 7.525 ± 0.4762 ng/ml, respectively." (PMID 28303973, 2017). "Together, these data indicated that transcription factor POU2F1 can directly regulate CTHRC1 expression in cervical cancer cells." (PMID 28303973, 2017). "The concentrations of CTHRC1 in serum of cervical cancer were significantly higher than those in CIN patients and healthy people." (PMID 28303973, 2017). "The expression of CTHRC1 in 303 cervical cancer tissues was significantly higher than those in normal cervical tissues in TCGA." (PMID 28303973, 2017). "Many microenvironmental factors are significantly altered by silencing of E6/E7, but we only studied the function of CTHRC1 in cervical cancer." (PMID 28303973, 2017). "In a dataset from GEO (GSE31056), the expression of CTHRC1 in 22 cervical cancer tissues increased compared to 12 normal tissues." (PMID 28303973, 2017). "Histological examination of the pulmonary tissue showed that CTHRC1 overexpression promoted the metastatic of cervical cancer in vivo." (PMID 28303973, 2017). "For example, CTHRC1 is elevated in cervical cancer and promotes metastasis via the Wnt/PCP pathway." (PMID 35307012, 2022). "For instance, CTHRC1 promotes cervical cancer metastasis and activates the Wnt/PCP pathway." (PMID 34968391, 2021).
cervical carcinoma (continued). "We next investigated the effects of CTHRC1 on cervical cancer cell migration and invasion in vitro." (PMID 28303973, 2017). "Moreover, silencing of CTHRC1 also suppressed cervical cancer cell invasion in vitro by transwell invasion assay." (PMID 28303973, 2017). "Moreover, the expression of CTHRC1 in 20 cervical cancer was higher than those in cervix uteri (n = 8), oral cavity (n = 9), palate (n = 1) and tonsil (n = 4) in Oncomine dataset." (PMID 28303973, 2017). "We first examined the effect of CTHRC1 overexpression/silencing on cervical cancer cell growth." (PMID 28303973, 2017). "We identified ED13, CTHRC1, LOXL2 and COP9 as cell invasion molecules impacting tumour progression in the ECM of endometrial and cervical cancer." (PMID 36982551, 2023). "We measured the serum levels of CTHRC1 in 72 healthy people, 74 CIN patients and 119 cervical cancer patients." (PMID 28303973, 2017). "Here, we examined whether CTHRC1 can affect the canonical Wnt pathway or the non-canonical Wnt pathway in cervical cancer cells." (PMID 28303973, 2017).
lung carcinoma (13 papers, 2014 to 2025). "To investigate CTHRC1 expression traits in lung cancer, we comparatively analyzed the CTHRC1 protein and mRNA profiles in different lung cancer cell lines and samples." (PMID 25238260, 2014). "Our data indicate that CTHRC1 contributes greatly to the development of lung cancer metastasis and invasion." (PMID 25238260, 2014). "However, large sample studies are scarce that focus on CTHRC1 expression and LUAD, which is the most common diagnostic subtype of lung cancer." (PMID 31798347, 2019). "Collagen triple helix repeat containing 1 (Cthrc1) has also been associated with the development of certain cancers, including lung cancer, therefore we decided to explore a possible interaction between miR-30b and Cthrc1 and the potential significance in the invasion and metastasis of NSCLC." (PMID 26388700, 2015). "Thus, we evaluated CTHRC1 functions in lung cancer cell migration and invasion." (PMID 29631554, 2018). "Previously, it was indicated that LAYN, CCT4, CTHRC1, and FHL1 gene were correlated with the migrational potential of lung cancer cells." (PMID 27586393, 2016). "However, more evidence still needed to determine the prognostic value of CTHRC1 in LUAD, which is the most common subtype of lung cancer." (PMID 31798347, 2019). "The in vitro siRNA-mediated MALAT1 silencing resulted in impaired lung cancer cell motility by altering the expression levels of cell motility-related genes, such as HMMR at pre-mRNA transcriptional level and CTHRC1, CCT4 and ROD1 at post-transcriptional level." (PMID 28253859, 2017). "Western blot and real-time RT-PCR analysis revealed that all lung cancer cell lines, including NCI-H226, NCl-H23, NCl-H820, NCl-H446 and A549, exhibited higher levels of CTHRC1 expression compared to that of primary human normal lung epithelial cells (Beas-2Bs) at both the protein and mRNA levels." (PMID 25238260, 2014).
prostate carcinoma (12 papers, 2014 to 2025). A carcinoma that arises from epithelial cells of the prostate gland. "Collagen triple helix repeat containing 1 (CTHRC1) is associated with tumor progression and reduced disease-free survival in prostate cancer." (PMID 40034825, 2025). "Downregulation of miR-30e-5p has been related to prostate cancer through its regulatory effect over CTHRC1, a protein upregulated in prostate cancer patients." (PMID 34811506, 2022). "CTHRC1 has a significant relation to EMT in prostate cancer." (PMID 38398019, 2024). "Therefore, the authors suggest using CTHRC1 as a potential therapeutic target for prostate cancer." (PMID 38398019, 2024). "While CTHRC1+ CAF were slightly elevated, ASPN+ and FAP+ CAF were comparable between ICC/IDC and Gleason pattern 5 prostate cancer." (PMID 36229464, 2022). "CTHRC1+, ASPN+, and FAP+ CAF were located peri-epithelial to ICC/IDC and were significantly enriched in ICC/IDC compared to benign prostate as well as Gleason pattern 3 and Gleason pattern 4 non-ICC prostate cancer." (PMID 36229464, 2022).
lung adenocarcinoma (10 papers, 2019 to 2025). A carcinoma that arises from the lung and is characterized by the presence of malignant glandular epithelial cells. "Shenet al. found that long noncoding RNA LINC00518 contributes to proliferation and metastasis in lung adenocarcinoma via the miR-335-3p/CTHRC1 axis." (PMID 37723874, 2023). "This study aimed to investigate the prognostic value of the potential biomarker collagen triple helix repeat containing 1 (CTHRC1) in lung adenocarcinoma (LUAD) patients." (PMID 31798347, 2019). "In lung adenocarcinoma, LINC00518 suppresses miR-335–3p, leading to increased levels of CTHRC1 and promoting tumor progression." (PMID 39108268, 2024). "Only CTHRC1 and LPAR5 were upregulated and MAGI1 was downregulated in lung adenocarcinoma, thyroid carcinoma, and kidney and renal papillary cell carcinoma in addition to invasive breast cancer when these genes were queried from TCGA database." (PMID 32539762, 2020). "Lung adenocarcinoma cell lines, including A549, GLC-82, SPC-A1, PC9, H1299 and H1975, exhibited higher CTHRC1 levels compared to that of primary human normal lung epithelial cells (BEAS-2B) and non-adenocarcinoma cell lines (L78 and H460)." (PMID 31798347, 2019).